RNU7-110P (RNA, U7 small nuclear 110 pseudogene)
Gene: Small nuclear RNA gene on chromosome 3 (33,414,150 to 33,414,211, forward strand). Ensembl gene ENSG00000252700.
Homologues: Orthologues: chimpanzee U7 (85% identical), macaque U7 (84% identical). Paralogues in human: RNU7-148P (85% identical), RNU7-111P (84% identical), RNU7-35P (81% identical), RNU7-97P (81% identical), RNU7-164P (79% identical), RNU7-24P (79% identical), RNU7-28P (79% identical), RNU7-45P (79% identical), RNU7-7P (79% identical), RNU7-113P (77% identical), RNU7-124P (77% identical), RNU7-13P (77% identical), and 142 more.